SPP1 (secreted phosphoprotein 1)
Diseases named in the same sentence as SPP1 in open-access papers (continued):
Sharing a sentence is not in itself a finding about the gene and the disease.
tumor (continued). "Recently, we have reported that CBX7 regulates several genes involved in tumor progression such as E cadherin, cyclin E, SPP1 likely accounting for the critical role of CBX7 in carcinogenesis." (PMID 28259135, 2017). "Previous studies reported the elevated expression of three SPP1 isoforms in tumour tissues and sera from GBM patients, and found an inverse correlation of its expression with patient survival." (PMID 28030801, 2017). "OPN was initially named “secreted phosphoprotein 1” because it was observed to be secreted from mammalian cells that had been transformed with tumor-promoting viruses." (PMID 29065446, 2017). "Altogether, our results show a novel mechanism of the transcriptional SPP1 regulation, which operates in malignant tumour cells containing a subpopulation of rare cells with stemness features." (PMID 28030801, 2017). "SPP1 modulates many functions of cancer cells: it stimulates cancer cell proliferation and invasion, and supports tumour angiogenesis and distant tumour outgrowth by instigating dormant tumours." (PMID 28030801, 2017). "The WT samples consistently expressed only very low levels of Spp1 while Spp1 expression in the tumor samples was more variable." (PMID 27282619, 2016). "All the tumor cell lines expressed higher levels of Spp1 than the wild-type mammary tissue but lower levels than the PMTs." (PMID 27282619, 2016). "This study highlights the significance of FN1 and SPP1 in the metastatic microenvironment based on the following evidences: First, the seeding and outgrowth of tumor cells were increased in the bleomycin-induced fibrotic lungs." (PMID 27329720, 2016). "In this study, we used both cell and mouse models to demonstrate that fibrotic microenvironment enhanced the seeding and consequently the outgrowth of tumor cells in the lungs by activating the FN1/SPP1-ITGAV pathway." (PMID 27329720, 2016). "Of the 9 genes tested, 8 (THBS1, CYR61, CTGF, MXRA5, SPP1, LTBP2, TGFBR1 and COL11A1) were found by qRT-PCR to be significantly differentially expressed in tumor-associated fibroblasts, for a validation rate of 89%." (PMID 26575166, 2015). "In summary, we demonstrated that all five isoforms of the single gene, SPP1, are co-expressed in the majority of primary EACs and act collectively in promoting tumor cell invasion and dissemination." (PMID 26068949, 2015). "We found that the expression of GPNMB and SPP1 was significantly higher in human GAMs isolated from GBM samples, when compared to non-tumor-associated control microglia and blood monocytes." (PMID 25658639, 2015). "Short hairpin RNA (shRNA) knockdown of SPP1 in NF1-MPNST cells reduced tumour spheroid size, wound healing and invasion in four different MPNST cell lines." (PMID 25884485, 2015). "The comparative transcriptome analysis reported here identified the SPP1 gene to be the single most differentially overexpressed gene in NF1-MPNSTs as compared to benign tumours." (PMID 25884485, 2015). "Here we report that SPP1/OPN was highly overexpressed in primary EACs and intracellularly localized to tumor cells." (PMID 26068949, 2015). "The SPP1 gene [NCBI: NM_001040058] (osteopontin; OPN) was found to exhibit the most significantly elevated differential mean expression level between the benign and malignant tumours." (PMID 25884485, 2015). "In BaP-treated A/J mice, the Spp1 serum concentration was significantly increased, and the tumor samples showed significantly increased Spp1 IHC staining compared with the control mice." (PMID 26565418, 2015). "The class of verified anti-apoptotic molecules overexpressed in cancer includes prominent tumor-associated proteins such as β-Catenin (CTNNB1), Osteopontin (OPN/SPP1), BMI1, Peroxiredoxin 3 (PRDX3;) and DAD1." (PMID 23717670, 2013). "These included genes known to be expressed by microglia (CCL8, SPP1, IRF7, IL1RAP), macrophages (IL1RN, SPP1, PDPN, IL1RAP, MDK, TFRC, HRH4), and tumor-associated macrophages (IL6, SPP1)." (PMID 22937035, 2012).
tumor (continued). "The SHH ligand gene and Gli-inducible target genes (FOXM1, IGF2, OSF2, H19, and SPP1) were overexpressed in tumour samples as compared with normal bladder tissue." (PMID 22361633, 2012). "Looking at the tumour grade, all the genes except MUC1 and SPP1 were significantly up-regulated in samples with a high tumour grade in Oncomine." (PMID 21314937, 2011). "Among the genes represented in the Met library, many are associated to tumor growth, invasiveness and metastasis, such as TM4SF1, LAMA4, G3BP2, CD59 antigen, and SPP1." (PMID 18211678, 2008). "Analysis of SPP1 protein expression in tumor and normal tissues indicated that SPP1 is present in the cytoplasm and nucleus of cells." (PMID 17989776, 2007). "Cells from SPP1 knockout mice show impaired colony formation in soft agar and slower tumor growth in vivo in comparison with tumors in wild-type mice." (PMID 17989776, 2007). "In our QRT-PCR analysis, SPP1 was overexpressed in 18 out of 22 samples from five different types of tumor tissues." (PMID 17989776, 2007). "In this study, we observed that biopsy samples had higher expression of SPP1 than samples from primary tumor resection and metastasis, showing that high levels of SPP1 are not necessary for tumor progression in OS." (PMID 17022822, 2006). "In this context, SPP1+ macrophages may represent a specialized TAM subset with potent tumor‐promoting capacity, consistent with prior reports linking macrophage heterogeneity to cancer aggressiveness." (PMID 41466485, 2026). "Additionally, LSCC was uniquely enriched for a pro-tumor SPP1+ macrophage subset with low phagocytic activity and high angiogenic potential, linked to poor prognosis." (PMID 42003920, 2026). "The infiltration of SPP1+ macrophages gradually increases with tumor progression, and their interaction with cancer cells gradually increases to reprogram malignant cells, leading to tumor upstaging and shaping of the desmoplastic microenvironment." (PMID 41466485, 2026). "SPP1 is a multifunctional integrin‐binding glycoprotein, which is overexpressed in a variety of tumors, playing a pivotal role in controlling the cell signaling pathway for tumor progression and metastasis." (PMID 41466485, 2026). "Finally, sender–receiver mapping demonstrated that SPP1 expression (Sender) was predominantly localized in tumor epithelial regions, while CD44 (Receiver) was enriched in immune cell–dense zones, particularly around macrophages and monocytes." (PMID 41201629, 2025). "Collectively, these results suggest a potential transcriptional shift coordinated by core TFs, suggesting that the tumor microenvironment may promote the epigenetic and regulatory reprogramming of Kupffer cells toward SPP1+ TAMs." (PMID 40725473, 2025). "In another study, SPP1+ TAMs were found to be enriched in the Wnt signaling pathway, which may support tumor growth." (PMID 40191203, 2025). "Furthermore, both APOE+ and SPP1+ macrophages showed a marked preference for the resistant tumor microenvironment." (PMID 40303328, 2025). "Notably, PLXDC1+ TPSCs, located near aggressive LRRC15+ myCAFs and SPP1+ macrophages, formed a desmoplastic and immunosuppressive niche around the tumor boundary, promoting CD8 T cell exhaustion." (PMID 40091495, 2025). "Furthermore, the CD44‒SPP1 axis is vital for cell‒cell communication and exerts significant immunomodulatory effects within the tumor microenvironment (TME)." (PMID 40524208, 2025). "In addition, tumor cells secreted SPP1 (often called osteopontin), which regulates tumor progression and correlates with poor prognosis in various cancers." (PMID 41279557, 2025). "Patients exhibiting high levels of both FAP+ fibroblasts and SPP1+ macrophages demonstrated the shortest progression-free survival period, suggesting the potential synergistic effects of these cell types in promoting tumor progression." (PMID 40191203, 2025).
tumor (continued). "CXCL13+ CD8+ T cells interacted with SPP1+ tumor-associated macrophages (TAMs) in non-recurrent tumors, while in recurrent tumors, they interacted with CD163+ TAMs." (PMID 40464813, 2025). "Spp1 expression was also strongly repressed in STING agonist–treated tumor cells in vivo." (PMID 40215177, 2025). "As ongoing research further elucidates the complex biology and interactions of SPP1+ macrophages within the tumor microenvironment, they are increasingly regarded as promising biomarkers and therapeutic targets that could improve patient outcomes." (PMID 41425545, 2025). "SPP1 was found to be associated with angiogenesis score in CD4+ T cells, which may be involved in tumour progression." (PMID 39231761, 2025). "Subsequently, we determine whether the tumor cells-secreted SPP1 could influence CD8+T cells function by regulating ITGA4/ITGB1 expression." (PMID 40665335, 2025). "Tacalcitol increased Spp1 mRNA expression in young 4T1 tumor-bearing mice." (PMID 40894304, 2025). "The presence of SPP1+BCL2A1+ TAMs is associated with an immunosuppressive tumor microenvironment in non-responders." (PMID 41225975, 2025). "For instance, although SPP1 is abundantly expressed in the tumor stroma, antibodies or small-molecule inhibitors may fail to achieve adequate intratumoral penetration due to ECM barriers or aberrant vascular architecture." (PMID 41391064, 2025). "Additionally, an enrichment of SPP1+ TAMs and hypoxic fibroblasts was noted in the tumor's hypoxic areas." (PMID 40432877, 2025). "In contrast, RCRC is dominated by an IS program, exhibits pronounced glycolysis (especially in MAC), heightened inflammatory states, and tumor cells concentrated near hypoxic cores and interacting with distinct immune cells (SPP1+ macrophages, CD161+ CD8 T cells)." (PMID 41450739, 2025). "Moreover, we find that SPP1 is only expressed in macrophages derived from tumour, which mainly exert effect on T cell subsets." (PMID 39934971, 2025). "In the context of bone metastasis, SPP1/OPN is also involved in osteoclast adhesion and bone resorption, raising the possibility that tumor-derived OPN may contribute to metastatic colonization and survival in the bone niche." (PMID 40753365, 2025). "Furthermore, SPP1-based co-culture experiments combined with Western blot, ELISA, and flow cytometry demonstrated that tumor-derived SPP1 regulates macrophage phenotypes and contributes to the immunosuppressive function of APOE+ macrophages." (PMID 40303328, 2025). "This study demonstrated that PLXDC1+ TPSCs could localize closely with basal‐like Mals and SPP1+ macrophages around the tumor boundary to generate a desmoplastic and immune‐suppressive niche." (PMID 40091495, 2025). "Moreover, the ICG signal accumulates in tumor stromal regions with higher vascular density and infiltrative macrophages expressing immunosuppressive markers, including Cd68 and Spp1." (PMID 41214366, 2025). "A large-scale study indicated that SPP1+ macrophages may exhibit immunosuppressive and tumor-promoting effects in patients with CRC, aligning with functions defined as IFN-TAMs." (PMID 40191203, 2025). "However, SPP1’s role in cancer is complex, as it can also exhibit a protective function in certain tumor types, acting as a “double-edged sword”." (PMID 41391064, 2025). "Moreover, SPP1+ macrophages interact with tumor cell CD44, synergizing with RNF32 to enhance cancer stemness via Wnt signaling." (PMID 41387204, 2025). "Focusing on the SPP1 pathway, its network visualization highlighted specific interaction directions among cell populations, with macrophages and T/B cells as dominant contributors, while tumor cells played a limited role." (PMID 41208987, 2025). "Compared to the corresponding normal tissue, SPP1 was highly expressed in tumor tissues." (PMID 38726780, 2025).
tumor (continued). "Importantly, pro-tumor CAFs form spatial niches with immunosuppressive SPP1+ macrophages and pro-angiogenic endothelial tip cells, collectively promoting an immune-excluded, pro-metastatic TME." (PMID 41450739, 2025). "Moreover, secreted phosphoprotein 1 (SPP1) positive macrophages interact with cancer-associated fibroblasts (CAFs) and tumor cells, promoting the formation of a tumor immune barrier (TIB) to prevent T cell infiltration." (PMID 41514551, 2025). "Additionally, we plan to isolate SPP1+ macrophages, co‐culture them with tumor cells, and investigate the impact and regulatory mechanisms of SPP1+ macrophages on tumor cells." (PMID 41176774, 2025). "To pinpoint the crucial factors mediating the interaction between PC cells and neutrophils, we analyzed intercellular communications involving ligand-receptor pairs and found that the SPP1 (tumor)–CD44 (neutrophil) signal was dramatically inhibited in the ZEB1 KD group." (PMID 40924501, 2025). "Specifically, their pro-metastatic capacity is driven by the enrichment of the SPP1+ macrophage subset, which enhances tumor cell invasiveness and remodels the ECM through secretion of osteopontin (SPP1) and CXCL12, thereby activating pathways such as the SPP1-CD44/PTGER4 signaling axis." (PMID 40109347, 2025). "SPP1 can promote tumor cell proliferation and tumor growth in HCC." (PMID 38726780, 2025). "There were studies which reported SPP1+ macrophages could interact with tumour cells and other immune cell types, leading to an immunosuppressive microenvironment." (PMID 39934971, 2025). "Nevertheless, our analysis of the TCGA data has demonstrated that COL3A1 and SPP1 show significant differential expression across AJCC tumor staging, and COL3A1 and PLAU show significant differences in T-staging, while COL3A1 and SPP1 are differentially expressed in N-staging." (PMID 41465316, 2025). "Interestingly, compared to normal tissues, SPP1+ TAMs-CAFs regulated tumor cells through the regulation of genes related to HCC tumorigenesis, including CCND1, MYC, CTNNB1, and BAX." (PMID 40230843, 2025). "Understanding the shared and unique features of SPP1+ TAMs across malignancies may offer new opportunities for targeted interventions aimed at disrupting their tumour‐promoting roles." (PMID 40395129, 2025). "Immune suppressive myeloid cells, such as SPP1 macrophages, prevent tumor T‐cell responses." (PMID 39639496, 2025). "Similarly, SPP1 interacts with integrins on tumor cells and activates the PI3K/AKT signaling pathway, a crucial driver of cell survival, proliferation, and migration." (PMID 41465316, 2025). "We observed that the SE signal was significantly correlated with the expression of the marker gene SPP1, suggesting that SEs may regulate the phenotype of SPP1+ TAMs in the tumor microenvironment." (PMID 40725473, 2025). "Specifically, tumor cells educated TANs to overexpress SPP1, GBP1, and ELOVL5, which subsequently activated three key mechanisms: promoting angiogenesis (SPP1-NF-κB-HIF/VEGF), immunosuppression (GBP1-NF-κB-PD-L1), and dysregulated oxidative lipid metabolism (ELOVL5-NF-κB), leading to poor prognosis." (PMID 41313078, 2025). "Recent studies indicate that SPP1 contributes to tumor growth through multiple pathways." (PMID 41391064, 2025). "In addition, we explored the mediators and downstream targets of the SPP1+ TAMs/CAFs-tumor cell axis." (PMID 40230843, 2025). "Similarly, secreted phosphoprotein 1 (SPP1) from CAFs diminishes the effectiveness of tyrosine kinase inhibitors (TKIs) by upregulating folate receptor alpha (FOLR1) in tumor cells." (PMID 40507341, 2025). "Importantly, the lead compound CANDI460 can down-regulate SPP1 both in vitro and in vivo, resulting in tumor remissions across multiple murine models, highlighting the therapeutic potential of targeting this macrophage subset." (PMID 41316282, 2025).
tumor (continued). "Moreover, high SPP1 expression strongly correlates with poor clinical outcomes, suggesting its role as a marker of aggressive tumor behavior." (PMID 40559389, 2025). "The CXCL9:SPP1 (CS) expression ratio, or CS polarity, has been identified as a key determinant of whether TAMs adopt an anti-tumor or pro-tumor phenotype." (PMID 40230843, 2025). "Similarly, our results validated that upregulated SPP1 enhances the proliferation, clonal formation and migration abilities of renal cancel cells, suggesting the essential role of SPP1 in promoting tumor progression." (PMID 40303328, 2025). "Additional analysis was conducted to determine whether the SPP1 protein produced by tumor can bind to the integrin α4/β1 protein in M1-polarized BMDMs or THP-1 cells." (PMID 40665335, 2025). "SPP1+ Tumor-associated Macrophages (TAMs) and cancer-related fibroblasts, which are immunosuppressive cells in the Tumor Immune Microenvironment (TIME) of HCC, form a Tumor Immune Barrier (TIB)." (PMID 38757323, 2025). "These macrophages interact with tumor cells via SPP1/CD44 axis." (PMID 41341850, 2025). "Furthermore, the polarization of CS macrophages (defined by CXCL9 and SPP1 expression) unveils a highly coordinated network encompassing variables that promote or suppress tumor progression." (PMID 40936719, 2025). "Conversely, in tumor-suppressive contexts, SPP1 may contribute to the maintenance of stromal homeostasis, thereby impeding the dissemination of malignant cells." (PMID 41391064, 2025). "Differentiation of SPP1 macrophages in tumor microenvironments depends on hypoxia." (PMID 41425545, 2025). "For example, SPP1 activates the PI3K/AKT pathway, leading to the phosphorylation and inactivation of pro-apoptotic proteins like BCL2-associated agonist of cell death (BAD) and caspase-9, thereby enhancing tumor cell survival." (PMID 40559389, 2025). "Notably, researchers found that tumor-associated neutrophils are enriched in the myeloid cell subtype, which is associated with poor prognosis, and CCL4, PD-L1, and SPP1 are promising targets for modulating this subtype." (PMID 41316282, 2025). "In conclusion, FAP+ fibroblasts could motivate the proliferation and tumor angiogenesis characteristics SPP1+macrophages." (PMID 40438108, 2025). "Given the complexity of the TME and the variety of tumor signaling pathways, a promising strategy might involve developing targeted therapies based on the specific tumor-promoting mechanisms driven by SPP1." (PMID 41391064, 2025). "Notably, macrophages from the tumor also had a significant upregulation of SPP1, an M2 marker recently reported to be a strong prognostic indicator of poor outcomes." (PMID 40848148, 2025). "Therefore, SPP1 serves not only as a functional mediator but also as a molecular marker identifying tumor-promoting macrophage populations." (PMID 41391064, 2025). "Furthermore, Mice injected with WT and ENO1-KO cells were treated with SPP1 inhibitor, revealing that ENO1 knockdown combined with SPP1 inhibitor treatment significantly inhibited tumor growth." (PMID 40665335, 2025). "CAFs have been shown to promote SPP1 expression in tumor cells, which promotes invasiveness." (PMID 40215177, 2025). "We further investigated the synergistic effect of SPP1+ TAMs-CAFs on tumor cells." (PMID 40230843, 2025). "SPP1 was highly expressed in macrophages, especially in tumor tissues." (PMID 41221295, 2025). "Furthermore, spatial transcriptomics research by Tong and colleagues demonstrated tumor-derived SPP1 activates PI3K/Akt pathways in HSCs, promoting their differentiation into cancer-associated fibroblasts (CAFs)." (PMID 41450464, 2025). "This strategy could involve blocking the interaction between SPP1 and its receptors or inhibiting its downstream signaling pathways to counteract its pro-tumor effect." (PMID 41391064, 2025).